CDK9 (cyclin dependent kinase 9)
Diseases named in the same sentence as CDK9 in open-access papers (continued):
Sharing a sentence is not in itself a finding about the gene and the disease.
cancer (continued). "The critical role played by CDK9 in facilitating RNA Pol II transcriptional elongation makes CDK9 inhibitors well suited for the treatment of cancers characterized by transcriptional dysregulation as a consequence of MYC amplification or MLL1 rearrangements." (PMID 41360777, 2025). "The cancer cell load among mice in the CDK9 knockdown group increased slightly but maintained a significant survival advantage." (PMID 39800696, 2025). "CDK7, CDK8, and CDK9 are desirable targets for therapy since they have shown oncogenic roles in a variety of cancer types, such as colorectal, ovarian, and breast malignancies." (PMID 40361480, 2025). "CDK9 activity is significantly upregulated in various cancers, enhancing the overexpression of downstream regulatory genes and promoting tumor progression." (PMID 40949156, 2025). "Another noteworthy application was in the identification of Toyocamycin as a selective CDK9 inhibitor in cancer cells, with a binding site characterization that opens the possibility for the design of novel CDK9 inhibitors." (PMID 40538444, 2025). "The step is found to be dysregulated in various types of cancers, and studies claim that CDK9 inhibition/degradation provides therapeutic benefits against cancer." (PMID 40361480, 2025). "Accordingly, targeting CDK9, or blocking its pathway of transcription, offers a potentially effective therapy for malignant tumors." (PMID 41360777, 2025). "Cyclin-dependent kinase 9 (CDK9) is crucial for several genes involved in cancer progression and HIV transcription in infected cells." (PMID 40230495, 2025). "For the first time, we report that activation of CDK7/CDK9–Rpb1 by nuclear stress mediates transcriptional regulation to prime paraptosis in cancer cells." (PMID 38858714, 2024). "St.38 which contains a triazole amide linker attached to the terminal chromene was the most potent compound among this series against the cancer cell lines and CDK9 enzyme, as well as this compound showed cell cycle arrest at the G0/G1 phase." (PMID 39404419, 2024). "For example, CDK9 inhibition is known to suppress highly expressed genes involved in cancer cell proliferation, metastasis, and treatment resistance, including MYC and MCL-1." (PMID 38172923, 2024). "The comprehensive approach presented in this study combines computational methodologies, experimental validation, and PROTAC technology to identify, characterize, and optimize a new class of CDK9 degraders for cancer therapy." (PMID 38534727, 2024). "Molecular docking studies indicated that both compounds fit well in the active sites of both CDK2 and CDK9, suggesting a mechanism for their action against cancer cells." (PMID 39404419, 2024). "This approach aims to identify and exemplify novel CDK9 degraders and explore the new territory of targeted protein degradation, steering a significant shift in cancer drug discovery." (PMID 38534727, 2024). "Herein, while initial responses to CDK9‐targeted therapies are observed in vitro across various KRAS‐mutant cancer types, their efficacy is far from satisfactory in nude mouse xenograft models." (PMID 39254172, 2024). "BRD4 and CDK9 have complementary and intimately connected roles in enhancing oncogenic gene expression programs in a variety of cancer types, especially in the context of MYC-driven tumors." (PMID 39117800, 2024). "Previously, we unexpectedly found that CDK9 inhibition also reactivates epigenetically silenced genes in cancer." (PMID 38172923, 2024). "Inhibition of cyclin-dependent kinase 9 (CDK9), a novel epigenetic target in cancer, can reactivate epigenetically silenced genes in cancer by dephosphorylating the SWI/SNF chromatin remodeler BRG1." (PMID 38172923, 2024). "Mechanistically, dinaciclib and NVP-2 treatment in cancer cells inhibit CDK9, preventing phosphorylation of RNA pol II and, thus, the initiation of elongation in mRNA transcription." (PMID 38769311, 2024).
cancer (continued). "Targeting CDK9 induces acute loss of MYC expression and potent cell apoptosis in many cancer models, and it has been reported to induce vulnerability in ibrutinib-resistant MCL cells." (PMID 38326887, 2024). "CDK9 and CYP3A4 are critical components of the complex network underlying cancer biology, and their inhibition represents promising targets for therapeutic intervention." (PMID 39498375, 2024). "Cyclin-dependent kinase 9 (CDK9) stimulates oncogenic transcriptional pathways in cancer and CDK9 inhibitors have emerged as promising therapeutic candidates." (PMID 39117800, 2024). "In the upcoming sections, we will present the computational and experimental methodologies employed in our investigation, along with results, thus highlighting their synergistic potential to drive the discovery of novel CDK9-targeted cancer therapeutics." (PMID 38534727, 2024). "Among the synthesized compounds, St.37 was the most potent derivative, exhibiting superior activity against two cancer cell lines with potent inhibitory effects on CDK9, as well as showed cell cycle arrest at the S phase." (PMID 39404419, 2024). "This public data supports CDK9 activity as a vulnerability in TNBC and the concept that CDDD11-8 inhibits cancer cell fitness by targeting CDK9." (PMID 38001268, 2024). "CDK9 inhibitors can selectively target fast-growing cancer cells by disrupting transcription elongation, which in turn hinders the production of proteins essential for cell cycle progression and survivaŚ." (PMID 39498375, 2024). "We propose a novel regulatory paradigm in which the activation of CDK7/CDK9–Rpb1 by nuclear proteostatic stress mediates transcriptional regulation to prime cancer cell paraptosis." (PMID 38858714, 2024). "In this study, a series of new molecules, KB-0742, a potent, selective, orally bioavailable small molecule inhibitor of CDK9 for MYC-dependent cancers, was relied upon." (PMID 39498375, 2024). "Since elevated transcriptional rate is a hallmark of many tumors, there is strong interest in targeting CDK9 to treat cancer." (PMID 39117800, 2024). "CDK9 has been recognized as a promising target for cancer therapy for more than a decade, prompting the formulation of numerous inhibitory compounds now in various stages of preclinical and clinical development." (PMID 38816355, 2024). "Cyclin-dependent kinase 9 (CDK9), a central player in transcription regulation and cell cycle progression, has emerged as a promising target to combat cancer." (PMID 38534727, 2024). "While CDK7 and CDK9 pathways have recently been targeted in cancer treatment, further elucidation is required regarding their involvement in the paraptotic program." (PMID 38858714, 2024). "Selective inhibition of the transcription elongation factor (P‐TEFb) complex represents a promising approach in cancer therapy, yet CDK9 inhibitors (CDK9i) are currently limited primarily to certain hematological malignancies." (PMID 39254172, 2024). "Its pivotal role in oncogenic pathways and the pressing need for novel cancer treatments has propelled CDK9 into the spotlight of drug discovery efforts." (PMID 38534727, 2024). "Since TNBC have key features of transcriptionally addicted cancers, targeting transcription via regulators such as cyclin-dependent kinase 9 (CDK9) has potential as a therapeutic strategy." (PMID 38001268, 2024). "Temporary suppression of CDK9 leads to the reduction in short-lived transcripts, ultimately inducing apoptosis in cancer cells." (PMID 39404419, 2024). "The findings underscore the potential of these compounds as lead candidates for further therapeutic development in pursuing innovative and effective cancer treatments, targeting CDK9." (PMID 38534727, 2024). "The study begins by emphasizing the pivotal role of CDK9 in transcription regulation and cell cycle progression, positioning it as a promising target for cancer treatment." (PMID 38534727, 2024).
cancer (continued). "MC180380, an inhibitor of cyclin-dependent kinase 9 (CDK9), is an efficacious anti-cancer agent worth advancing further toward clinical use." (PMID 38172923, 2024). "CDK9 drives vital oncogenic pathways, and its frequent overexpression across various cancer types emphasizes its significance as a prime target for cancer therapy." (PMID 38534727, 2024). "CDK9 plays a crucial role in the initiation and advancement of various cancers, contributing significantly to tumorigenesis, as its inhibition is a promising strategy against cancer." (PMID 38139304, 2023). "There is satisfactory evidence that supports the role of CDK9 in cancer via controlling proapoptotic proteins and the promotion of cell proliferation." (PMID 37513929, 2023). "Cyclin-dependent kinase 9 (CDK9)-dependent signaling induces transcription of downstream oncogenes promoting tumor growth, especially in hyperproliferative ‘oncogene-addicted’ cancers, such as human hematological malignancies (HHMs)." (PMID 38117531, 2023). "The most potent compound 2g inhibited cancer cell proliferation by blocking Rb phosphorylation and induced apoptosis via downregulation of CDK9 downstream proteins Mcl-1 and c-Myc in MIA PaCa-2 cells." (PMID 36656085, 2023). "In conclusion, most CDK9 inhibitors and degraders have only been studied in cancer cells in vitro or in mouse models in vivo, and few clinical studies have been completed owing to drug side effects." (PMID 37272701, 2023). "CDK9 is involved in the transcriptional elongation of several target genes, is widely expressed, and contributes to various cancers such as pancreatic, prostate and breast cancer." (PMID 36986673, 2023). "CDK9 has been previously established as a target in cancer using genetic and pharmacologic depletion strategies." (PMID 36998071, 2023). "This intermittent inhibition strategy can allow for anti-cancer activity while minimizing the unacceptable toxicity that besets CDK9 inhibitors with longer half-lives." (PMID 38117531, 2023). "As a catalytic subunit of P-TEFb, CDK9 plays a critical role in tumorigenesis and progression in a variety of cancers, including hematologic malignancies and solid tumors." (PMID 37272701, 2023). "Based on the high potency of CDK9 inhibition as a cancer cell-selective TRAIL-sensitizing strategy, we believe this is a potent new anti-cancer strategy." (PMID 36979907, 2023). "Wang and coworkers utilized a strategy focused on substitution of both the A- and B-rings of wogonin at C8 and C4′, respectively, in search of optimized cyclin-dependent kinase 9 (CDK9) inhibitors for the treatment of cancer." (PMID 37892857, 2023). "The current study aims to further develop the novel imidazopyrazine scaffold targeting CDK9 in cancer." (PMID 37513929, 2023). "CDK9 dysregulation leads to uncontrolled oncogene transcription and carcinogenesis; thus, CDK9 is a promising therapeutic target for cancer." (PMID 37272701, 2023). "LncRNAs are also known to control the cell cycle progression of cancer cells through cyclin-dependent kinase 9 (CDK9)." (PMID 36902032, 2023). "Though several agents targeting CDK9 to inhibit cell growth are being investigated as cancer therapeutics, many show significant cross-reactivity with other members of the CDK family." (PMID 38117531, 2023). "Immunohistochemical analysis of CDK9 expression in cancer and normal tissues of CRC specimens was performed." (PMID 36979907, 2023). "Emerging evidence suggests that some CDK9-related negative regulators (e.g., HEXIM 1/2, LARP7, and MePCE) are also involved in CDK9-related diseases, e.g., cancers." (PMID 35088192, 2023). "For example, LARP7 downregulation has been confirmed in several cancers, which subsequently potentiates CDK9-mediated transcription elongation and promotes cancer growth and metastasis." (PMID 35088192, 2023).
cancer (continued). "Taken together, these results showed that CDK9 upregulation also contributes to the overproliferative and antiapoptotic phenotypes of PH PASMCs similar to that observed in cancer cells." (PMID 35088192, 2023). "Inhibition with GFH009 hampers expression of cell growth-promoting molecular targets downstream of CDK9, including several cancer-protecting anti-apoptotic proteins." (PMID 38117531, 2023). "A number of CDK9 inhibitors have been utilized as the therapeutic potential for anti-cancer drugs, and some of them have entered different phases of clinical trials." (PMID 37537243, 2023). "As previously observed in cancer cells, CDK9 upregulation was also detected in both pulmonary arterial tissues from MCT-induced PH rats and hypoxia-treated HPASMCs in the present study." (PMID 35088192, 2023). "It has been demonstrated that CDK9 mediates apoptotic resistance via transcriptionally controlling the overexpression of anti-apoptotic proteins in cancer cells such as c-FLIP and Mcl-1." (PMID 36979907, 2023). "Cyclin-dependent kinase 9 (CDK9) is a transcription-regulating protein that has recently gained attention after promising in-vivo and in-vitro trials in multiple human cancers." (PMID 36374405, 2023). "Since the recognition of CDK9 as a therapeutic possibility for treating cancer, large pharmaceutical companies have developed several scaffolds as CDK9 inhibitors." (PMID 37513929, 2023). "In summary, these data suggest that bis-DbTACs are effective degraders of CDK6 and CDK9, providing a basis for their potential applications in cancer treatment." (PMID 37495569, 2023). "GL-V9 has anti-cancer solid action, while compound 51 is selective for CDK9 overexpressing cancer cells and suppresses the proliferation of MV4-11." (PMID 37446743, 2023). "Previous studies have found that targeting CDK9 in cancers can inhibit oncogenes (e.g. MYC) and reactivate tumor suppressor genes (e.g. CHD5)." (PMID 35394046, 2022). "Dynamic BH3 profiling revealed that, mechanistically, combining TRAIL with CDK9 inhibition induced a drastic increase in the mitochondrial priming of cancer cells." (PMID 34535764, 2022). "We here identify the combination of the specific inhibition of the kinase activity of CDK9 with the agonistic activation of TRAIL death receptors as a highly effective means to induce apoptosis across a wide range of cancer entities." (PMID 34535764, 2022). "CDK9 belongs to a family of CDK enzymes responsible for cell proliferation and development, which has been reported to be associated with cancer progression in many cancer types." (PMID 36157222, 2022). "For example, the ability of CDK9 inhibitors to sensitize cancer cells to traditional chemotherapy warrants investigation." (PMID 35164752, 2022). "The anti-cancer activity of CDK9 inhibitors relies largely on the rapid turnover rate of the oncoprotein target, as well as the critical dependence of the cancer cells on the sustained expression of the oncoprotein for survival." (PMID 35383271, 2022). "Dissecting these responses has the potential to identify those that are cancer cell-selective, which can subsequently be targeted in combinatorial treatment strategies with CDK9 inhibitors." (PMID 35708495, 2022). "The persistent demand for CDK9 renders cancer cells highly vulnerable to its inhibition when compared to non-transformed cells." (PMID 35267421, 2022). "Recently, Wang and co-workers designed and synthesized a series of cyclin-dependent kinase 9 (CDK9) inhibitors with cancer stem cell (CSC) inhibition activity for non-small-cell lung cancer (NSCLC) therapy." (PMID 35268851, 2022). "Based thereupon, we propose the combination of TRAIL receptor agonists with drugs capable of inhibiting CDK9 for clinical evaluation in a wide variety of cancers." (PMID 34535764, 2022). "Based on the data presented here, and in previous studies, CDK9 inhibition triggers adaptive responses at multiple levels to allow cancer cell survival." (PMID 35708495, 2022).
cancer (continued). "In either case, their respective CDK9-inhibitory activity was both, required and sufficient for their capacity to sensitize cancer cells to TRAIL-induced apoptosis." (PMID 34535764, 2022). "CDK9 inhibition produces a drastic reduction in global mRNA production and also downregulates highly expressed genes that are essential for cancer cell proliferation, metastasis, and treatment resistance." (PMID 35884401, 2022). "The drug candidate has potential to overcome cancer cell resistance to FLT3 inhibition by concurrently blocking the CDK9-mediated upregulation of cancer cell-survival genes." (PMID 35267421, 2022). "Enhanced CDK9 activity is detected in several cancer entities, resulting in increased transcription of cancer-promoting genes." (PMID 36399280, 2022). "The overactivation of CDK9 in cancer cells drives the constant production of short-lived proto-oncogenes and anti-apoptotic proteins (e.g., MYC, MCL-1, and XIAP) that are important contributors to neoplastic transformation." (PMID 35267421, 2022). "Cyclin-dependent kinase 9 (CDK9) plays a critical role in transcriptional elongation, through which short-lived antiapoptotic proteins are overexpressed and make cancer cells resistant to apoptosis." (PMID 36615314, 2022). "Owing to its crucial function in transcription elongation and the fact that cancer cells demand high transcriptional activity, CDK9 has emerged as a potential drug target for many cancer types." (PMID 35442775, 2022). "CDK9 is deregulated in hematological malignancies and other cancer types, prompting the development of CDK9 inhibitors." (PMID 35567477, 2022). "CDK9 inhibitor compounds, currently deployed in clinical trials as anti-cancer treatments, can be applied experimentally to curtail early neutrophilic inflammation." (PMID 34523672, 2022). "CDK7 and CDK9 stand out as the most relevant targets, albeit through distinct mechanisms of oncogenicity and context-dependent contributions to cancer survival and drug sensitivity." (PMID 36577800, 2022). "As proof of concept, we focused on CDK9—a cancer target whose clinical development has been hampered by compounds with poorly understood target specificity and unacceptable toxicities." (PMID 35442775, 2022). "Altogether, we demonstrated that toyocamycin exhibits specific CDK9 inhibition in cancer cells, highlighting its potential for cancer chemotherapy." (PMID 35884401, 2022). "Overall, these results establish a versatile in vivo target validation platform that can be employed for rapid triaging of therapeutic targets and lend support to efforts aimed at advancing CDK9 inhibitors for cancer therapy." (PMID 35442775, 2022). "Beyond establishing our modeling approach, our results provide information relevant to the clinical development of CDK9 inhibitors for cancer." (PMID 35442775, 2022). "Pharmacological inhibition of CDK9 induces apoptosis in cancer cells, making it a potential drug target in oncology." (PMID 36615314, 2022). "CDK9 inhibitors showed broad anti-cancer activity in-vivo and in-vitro, but the results from clinical trials are still uncertain." (PMID 35092513, 2022). "The expression of CDK9 was higher in cancer than in normal urothelial tissue and correlated with tumor grade, stage, and invasiveness." (PMID 35326643, 2022). "Remarkably, the combination of TRAIL with CDK9 inhibition was also highly effective on cancers resistant to both, standard-of-care chemotherapy and various targeted therapeutic approaches." (PMID 34535764, 2022). "It was expected that such modifications would improve the antiproliferative activity of these molecules against cancer cells by increasing their affinity for the CDK9 enzyme." (PMID 36615314, 2022). "One of them demonstrated proteasome-dependent degradation of CDK9 (DC50 = 9 nM after 16 h) in three cancer cell lines (MOLT4, 293T, K562)." (PMID 36235168, 2022).